RNU6-618P (RNA, U6 small nuclear 618, pseudogene)
Gene: Small nuclear RNA gene on chromosome 12 (31,396,390 to 31,396,501, forward strand). Ensembl gene ENSG00000200388.
Homologues: Orthologues: chimpanzee U6 (97% identical), guinea pig U6 (87% identical), macaque U6 (86% identical), rabbit U6 (79% identical), pig U6 (74% identical). Paralogues in human: RNU6-29P (88% identical), RNU6-38P (88% identical), RNU6-1 (86% identical), RNU6-1145P (86% identical), RNU6-15P (86% identical), RNU6-16P (86% identical), RNU6-2 (86% identical), RNU6-25P (86% identical), RNU6-39P (86% identical), RNU6-3P (86% identical), RNU6-41P (86% identical), RNU6-4P (86% identical), and 1289 more.